HAS1 (hyaluronan synthase 1)
Diseases named in the same sentence as HAS1 in open-access papers (continued):
Sharing a sentence is not in itself a finding about the gene and the disease.
tumor (continued). "Several genes such as Csf2, Has1, Ccl22 and Tnf induced by ruxolitinib and inhibited by IKK-16 are associated with driving tumor-promoting functions in macrophages and increasing survival of tumor cells." (PMID 37005447, 2023). "Analysis of serum samples from 59 patients with EC and 22 healthy postmenopausal women further indicated that elevated HAS1 expression correlates with the depth of myometrial invasion, the degree of histologic malignancy of the tumor, or the involvement of the lymphovascular space." (PMID 36830841, 2023). "In comparison, HAS1 expression in tumour cells was low to medium measured in 5 of 12 samples." (PMID 35767191, 2022). "The higher level of HAS1 expressed in the RFs compared to the PFs might be one of the reasons that the RFs favor tumor ingrowth." (PMID 36232952, 2022). "In this study, although the HA content did not exhibit a prognostic value, an association between tumor grade and HAS1, HAS2, and HYAL-2 was observed, and an increase in HAS2 was also correlated with a poor prognosis of the patients." (PMID 33744285, 2021). "By contrast, HAS-1 negative expression in tumor cells was significantly associated with features of aggressiveness, such as higher mitotic index, presence of atypical mitoses, and poor disease outcome." (PMID 34066306, 2021). "HAS-1 was also detected in tumor cells, with a more intense pattern in carcinomas." (PMID 34066306, 2021). "In tumor tissues, HAS1 is typically expressed in tumor cells, as well as in stromal fibroblasts." (PMID 25699059, 2015). "HAS1 is a member of gene family HA, which has been correlated with tumor metastasis." (PMID 19874631, 2009). "The study demonstrated that HAS1 type HA-synthase is expressed in BC cells and the expression is upregulated, both at the transcriptional and translational levels, suggesting that HAS1 expression may have prognostic potential related to tumor recurrence and progression." (PMID 38372785, 2024). "Therefore, another possible explanation for the association of low HAS3 expression with a more favorable outcome may be that HAS3 is elevated in early tumor stages and HA synthesis is taken over by HAS1 and HAS2 during progression." (PMID 24069434, 2013). "In comparison, mouse fibroblasts from KPT tumors were enriched with cells highly expressing tumor-suppressing inflammatory CAF (iCAF) markers, including Has1, Ccl2, Il6, and Cxcl2 (clusters 1–3)." (PMID 41480763, 2026). "High HAS1 expression in conjunction with low HYAL1 and HYAL2 expression was observed in the tumor stage, which resulted in the accumulation of HA around tumor cells." (PMID 39858106, 2025). "By measuring the maximum invasion distance of HN6, HSC3, and CAL27 tumor spheroids on dECM derived from CAFIF-NC and CAFIF-shHAS1, we observed that knockdown of HAS1 in CAFIF significantly impaired the pro-invasive capacity of CAFIF-derived ECM (p < 0.05)." (PMID 40813707, 2025). "Tumor cells express HAS1–3 throughout the disease course, whereas expression of HYAL1 and 2 decrease in the tumor stage, leading to HA accumulation." (PMID 39858106, 2025). "HA production was also evaluated by immunohistochemistry analysis of HAS1, HAS2, HAS3, HYAL1, and HYAL2 expression on tumor cells." (PMID 39858106, 2025). "It is likely that HAS1 and HAS3 act cooperatively with HAS2 to support HA deposition and tumor growth." (PMID 39946200, 2025). "In this research, the ERGS was composed of 8 ERGs (CXCL9, CYP17A1, DRGX, ENTHD1, HAS1, LAIR2, RETN, and SPHKAP), some of which were pivotal to the tumor progression." (PMID 38600248, 2024). "We first analyzed HA synthases HAS1, HAS2, and HAS3, hyaluronidases HYAL1 and HYAL2, ABCC5 transporter, and CD44 expression in tumor tissue (TT) in TCGA database." (PMID 39039104, 2024). "The results show that HAS1 was overexpressed in effusions, HAS2 was overexpressed in solid metastases and primary tumours, and HAS3 was overexpressed in primary carcinomas and effusions." (PMID 35767191, 2022).
tumor (continued). "On the other hand, several members of the HA signaling pathway, like HA synthases (HAS1, HAS2, HAS3), HA receptors and hyaluronidases (mainly HYAL1) are critical determinants of growth and progression of the tumor." (PMID 32610620, 2020). "It is well known that members of the family of molecules of the HA signaling pathway, like HA synthases (HAS1, HAS2, HAS3), HA receptors and hyaluronidases (mainly HYAL1) are critical determinants of tumor growth and progression." (PMID 32610620, 2020). "HA synthesis by HAS1-3 and its deposition into the ECM is increased during EMT and is known to play a crucial role during tumor progression." (PMID 28086235, 2017). "Autocrine and paracrine signals instruct tumor and stroma cells to deposit HA into the ECM, synthesized by three hyaluronic acid synthases (HAS1-3)." (PMID 28086235, 2017). "In invasive tumor stages RHAMM-, HAS1 and HAS2 mRNA-expression levels were elevated whereas HAS3v1 was reduced as compared to non-invasive tumors." (PMID 24069434, 2013). "In our data, the staining pattern of the lymph node metastases resembled that of the primary tumor, but the amount of CD44 and HAS1 were further reduced in the metastases compared to deep melanomas." (PMID 23560496, 2013). "Finally, based on RNA-seq findings, we knocked down hyaluronan synthase 1 (HAS1) in CAFIF to evaluate its role in extracellular matrix (ECM) remodeling and tumor invasion." (PMID 40813707, 2025). "HAS1 and HAS2 expression increases following malignant transformation and promotes tumor growth." (PMID 38372785, 2024). "Similarly, high expression of HAS1 and HAS3 either tumor tissue or tumor stroma predicts poor prognosis or malignant progression in breast cancer, lung cancer, bladder cancer, and also chondrosarcoma." (PMID 36698043, 2023). "Notably, we also found an interaction between HAS1-2 and VCAN, which is an essential proteoglycan supporting growth, survival, angiogenesis, metastasis, migration and invasion of tumour cells." (PMID 35767191, 2022). "Thus, the median transcript levels of hyaluronic acid synthase 1 (HAS1) and major HA receptors CD44 and RHAMM were elevated 3 to 25-fold in those tumor tissues when compared with normal tissues." (PMID 35528727, 2022). "Negative HAS-1 staining in tumor cells was also more frequently observed in female patients and at lower age of onset." (PMID 34066306, 2021). "The clusters 1, 7 and 8 highly expressed steroidogenic genes STAR as well as tissue remodeling genes HAS1, ADAMTS1 and ADAMTS4, consistent with theca-stromal cells from ovary, which might be included from non-tumor tissues from ovaries." (PMID 34257564, 2021). "We show that HAS1, HAS2 and HYAL2 associate with tumor grade (WHO II-IV), and HAS2 is a negative prognostic factor in diffusely infiltrating astrocytomas." (PMID 29914429, 2018). "Expression of tumor cell HAS1, but not HAS2 or HAS3, was found to correlate with reduced overall survival when breast cancer patients were not sorted into subtypes." (PMID 26106384, 2015). "Furthermore, mRNA expression of HAS1 and HAS2 were significantly upregulated in muscle-invasive tumor stages (pT2, pT3 and pT4)." (PMID 24069434, 2013). "We additionally observed that HAS1 is alternatively spliced in tumor cells derived from effusions, but not in solid specimens." (PMID 23202930, 2012). "Some types of cancer cells express hyaluronan synthases (HAS1, HAS2, and HAS3), as well as fibroblasts and chondrocytes as part of the extracellular matrix, and the signaling between HA and CD44 is deemed critical for tumor proliferation and the spread of cancer." (PMID 40011711, 2025). "In fact, although with no statistical significance comparing the different subgroups, both in tissue blood vessels and in tumor cells, ACC showed a higher rate of HAS-1 intense (3+ score) staining, which might explain the overexpression observed at the gene level." (PMID 34066306, 2021).
tumor (continued). "Among these, osteopontin is selectively expressed in ACC tumor cells and represents a potential diagnostic marker, although with a remarkably low sensitivity, whereas negative HAS-1 expression in tumor cells characterizes a subset of ACC with a more aggressive clinical outcome." (PMID 34066306, 2021). "When comparing TT and NAT, we noticed a high variability of HAS2, HAS3 and HYAL2 among the patients for both tumor types while HAS1 and HYAL3 could not be detected." (PMID 32610620, 2020). "It has to be highlighted that stromal cells play a pivotal role in producing abnormal amounts of HA, and in these cells, HAS1, and not HAS2, is the strongest isoform affecting tumor relapse and patient prognosis." (PMID 37568628, 2023). "MSGN1, ISM2, HAS1, RETN, MMP19, C1QTNF1, and F13A1 were all involved in the regulation of tumors, but their involvement in the regulation of tumor immunity is not clear." (PMID 34177903, 2021). "Whereas the expression of HAS1 and HAS2 correlated with the content of hyaluronan in tumor tissue, and their expressions are not altered until the invasive phase of the disease, at which time hyaluronan content decreased." (PMID 27184066, 2016). "Tumor tissue of lymph node positive patients showed higher RHAMM and HAS1 mRNA expression levels compared to those with negative lymph node status." (PMID 24069434, 2013). "However, the lack of a direct correlation between HAS-1 gene and protein data in ACC vs. ACA might be explained by the wide heterogeneity of protein distribution and intensity in blood vessels, as well as in tumor cells." (PMID 34066306, 2021).
cancer (31 papers, 2009 to 2025). A tumor composed of atypical neoplastic, often pleomorphic cells that invade other tissues. "The prognostic significance of HAS-1 in cancers is equivocal and has been studied either in cancer cells or in cancer stroma, including cancer-associated fibroblasts." (PMID 34066306, 2021). "To avoid the uncertainties inherent in genome-wide association studies, we sought susceptibility polymorphisms in a candidate gene, HAS1, based on the biology of the gene in cancer patients." (PMID 24950197, 2014). "Aberrant pre-mRNA splice variants of hyaluronan synthase 1 (HAS1) have been identified in malignant cells from cancer patients." (PMID 23301075, 2013). "Curiously, the statistical significance for the cancer-associated increase of HAS immunoreactivity was strongest for HAS1 although real-time RT-PCR suggested very low transcription of this gene." (PMID 20875124, 2010). "Using different cells and expression systems as models, we demonstrated that HAS1 expression induced clonal diversity, multi-nucleus formation, micronucleus generation, centrosome abnormalities which are the most common cancer-associated cellular anomalies found in histological studies." (PMID 29137675, 2017). "Some types of cancer cells express hyaluronan synthases (HAS1, HAS2, and HAS3), as well as embryonic cells, and HAS2-CD44 signaling is considered to play a vital role in malignant progression." (PMID 37064130, 2023). "HAS1 and HAS2, as key enzymes in HA synthesis, are significantly positively correlated with the degree of CAF infiltration in most cancers, but HAS1 is significantly negatively correlated with the degree of CAF infiltration in LGG." (PMID 37636435, 2023). "In this study, a pan-cancer analysis of the three enzymes called hyaluronan synthases (HAS1, HAS2, and HAS3) that produce HA was performed." (PMID 37636435, 2023). "Our study indicates that HAS1, 2, and 3 share commonalities and unique characteristics across different types of cancer." (PMID 37636435, 2023). "HAS1 mRNA were overexpressed in effusions, in contrast to primary carcinomas and solid metastases, whilst HAS2 mRNA was overexpressed in solid metastases and primary carcinomas compared to effusions and HAS3 mRNA was overexpressed in all subtypes." (PMID 29510526, 2018). "Our results also indicate that intracellular HA produced by HAS1 is associated with the BRCA1-RHAMM-microtubule complex, which implies a possible mechanistic role in cancer initiation and progression." (PMID 29137675, 2017). "Among three isoenzymes, HAS2 and HAS3 have been shown to produce extracellular HA, whereas HA synthesized by HAS1 has been identified in both intra- and extracellular compartments of cancer cells." (PMID 29137675, 2017). "The intracellular HA produced by HAS1 can aggravate genomic instability and intratumor heterogeneity, pointing to a fundamental role of intracellular HA in cancer initiation and progression." (PMID 29137675, 2017). "HAS1 mRNA was overexpressed in effusions compared to primary carcinomas and solid metastases (p < 0.001), and an alternatively spliced HAS1 was expressed only in effusions." (PMID 23202930, 2012). "HAS1-positive cells were not present in any of the normal specimens or in the stroma of cancers, but 41% of the cancer samples had a low percentage of HAS1 positive cancer epithelial cells." (PMID 19435493, 2009). "Therefore, we utilized public databases and tools to provide a comprehensive description of the characteristics of HAS1, 2, and 3 across cancers and the potential biological pathways involved at the molecular, protein, cellular, and clinical sample levels." (PMID 37636435, 2023). "Thus, these clinical data support the research observations on HAS1’s functional role in cancer development and differentiation." (PMID 36613567, 2022). "On the other hand, HAS1‐positive fibroblasts were distant from cancer cells, as expected." (PMID 32931156, 2020).
cancer (continued). "Our results demonstrate that an increase in cytoplasmic HA through overexpression of HAS1 in different human cell types increases the characteristic cancer phenotypes of clonal variation, EMT, micronucleation and centrosome abnormalities such as clustering and/or fragmentation." (PMID 29137675, 2017). "Most of the previous studies on HA synthesized by HAS2 and HAS3 were focused mainly on its roles in the ECM and signal transduction, whereas the majority of HAS1 research has focused on prognostic marker studies or expression profiles of HAS1 genes in different cancers." (PMID 29137675, 2017). "Accumulating evidence has led to the hypothesis that HAS1 in these cancer cells may produce intracellular HA which competes with the mitotic apparatus for RHAMM binding and thus protect the cells from RHAMM-mediated mitotic arrest." (PMID 26448754, 2015). "In addition, WTAP also regulates the expression of certain genes associated with cancer cell movement, such as chemokine ligand 2 (CCL2), CCL3, matrix metalloproteinase 3 (MMP3), lysyl oxidase like 1 (LOXL1), hyaluronic acid synthase 1 (HAS1) and thrombospondin 1 (THBS1)." (PMID 32943100, 2020). "The study comprehensively describes the characteristics of HAS1, HAS2, and HAS3 in cancers using public databases and tools, to identify the potential biological pathways involved at the molecular, protein, cellular, and clinical sample levels." (PMID 37636435, 2023). "In recent years, an increasing number of researchers have focused on the relationship between tumorigenesis and HAS1 and showed the role of HAS1 in the growth of RCC and other malignant tumors." (PMID 36010674, 2022). "HAS1, HAS2, and HAS3 were overexpressed in effusions, solid metastases, and primary carcinomas, respectively." (PMID 26579497, 2015). "Furthermore, HAS1 and HAS3 knockdown reduce cancer progression and metastasis in breast and osteosarcoma models." (PMID 36613567, 2022). "A dose-dependent reduction in the mRNA levels of HAS2 or HAS3 was observed in all the cancer cell lines examined, which is not consistent with the findings of the current study, in which Has1 and Has3 mRNA levels increased after treatment with MU." (PMID 22045192, 2011). "The levels of HAS2 and HAS3 mRNA (HAS1 was low or absent), were not consistently increased in the carcinomas, and were not significantly correlated with HAS protein or hyaluronan accumulation in individual samples." (PMID 19435493, 2009). "Besides, WTAP regulates the expression of certain genes related to motility of cancer cells, such as chemokine ligand 2 (CCL2), chemokine ligand 3 (CCL3), matrix metallopeptidase 3 (MMP3), lysyl oxidase-like 1 (LOXL1), hyaluronan synthase 1 (HAS1), and thrombospondin 1 (THBS1)." (PMID 30062093, 2018). "In addition, the relative importance of stromal versus tumour cell HAS expression has not been addressed experimentally in any cancer yet, which is due to the fact that HAS2 deficient mice are lethal and HAS1 and HAS3 deficient mice are not available to the scientific community." (PMID 21429221, 2011). "Of note, cancer cells were also positive for LIF, SEMA7A, and HAS1, while they were negative for αSMA." (PMID 32931156, 2020). "There was little HAS1 mRNA, no consistent upregulation of HAS2 in the cancers, and the median values of HAS3 mRNA were actually lower in cancers than controls." (PMID 19435493, 2009).
infection (4 papers, 2009 to 2024). The state of being infected such as from the introduction of a foreign agent such as serum, vaccine, antigenic substance or organism. "Intriguingly, this analysis identified the enzyme Has1, which was upregulated during infection, as the most downregulated gene following IL-13 neutralization." (PMID 34185704, 2021). "The data showed that HAS1 mRNA expression increased after infection and was maintained at all time points." (PMID 19876387, 2009). "We found that the major hyaluronan synthase expressed in the lung is HAS1, and that its expression was increased after infection with Mycobacterium tuberculosis." (PMID 19876387, 2009). "Total RNA was extracted from the lungs after 1, 3, 5, 7, 14, and 21 days of infection, and analyzed for HAS1, HAS2, and HAS3 mRNA transcription by reverse transcriptase-polymerase chain reaction (RT-PCR)." (PMID 19876387, 2009). "To see if hyaluronan is present at the site of infection of M. tuberculosis, we assessed the expression of hyaluronan synthases (HAS1, HAS2, and HAS3) in the lungs of BALB/c mice infected with the M. tuberculosis H37Rv strain, using the low-dose aerosol infection model." (PMID 19876387, 2009).
inflammation (3 papers, 2015 to 2021). Aberrant reaction of the microcirculation characterized by movement of fluid and leukocytes from the blood into extravascular tissues. "In a murine model of knee joint cartilage damage, a deficiency of HAS1 triggered chronic joint inflammation and was associated with widespread intra-articular fibrosis." (PMID 30704030, 2019). "The function of HAS1 is not entirely understood, but it may also regulate HAS2 and metabolism of inflammatory matrices post-injury as HAS1-deficient mice develop chronic joint inflammation and severe intra-articular fibrosis following cartilage injury." (PMID 34416923, 2021).
adenocarcinoma (2 papers, 2015 to 2022). A common cancer characterized by the presence of malignant glandular cells. "Theproportion of HAS-1-positive epithelial cells tended to be significantly lower insquamous cell carcinoma and adenocarcinomas than in pre-neoplastic lesions (P=0.05)." (PMID 26352698, 2015).
blood cancer (1 paper, 2014). "In some blood cancer patients, HAS1 is a hypermutated gene that undergoes aberrant splicing to generate splice variants that correlate with poor survival." (PMID 24950197, 2014).